IL36RN (interleukin 36 receptor antagonist)
Description:
Inhibits the activity of interleukin-36 (IL36A,IL36B and IL36G) by binding to receptor IL1RL2 and preventing its association with the coreceptor IL1RAP for signaling. Part of the IL-36 signaling system that is thought to be present in epithelial barriers and to take part in local inflammatory response; similar to the IL-1 system with which it shares the coreceptor. Proposed to play a role in skin inflammation. May be involved in the innate immune response to fungal pathogens, such as Aspergillus fumigatus. May activate an anti-inflammatory signaling pathway by recruiting SIGIRR.
Synonyms: IL-36Ra; IL-1F5; FIL1D; IL1F5; IL1HY1; IL1L1; IL1RP3; FIL1; FIL1(DELTA); IL36RA; MGC29840; PSORP; PSORS14
Tractability: Antibody: UniProt places it where antibodies can reach, with high confidence; its Gene Ontology location is reachable by antibodies, with high confidence.
Gene: Protein-coding gene on chromosome 2 (113,058,638 to 113,065,382, forward strand). Ensembl gene ENSG00000136695.
Subcellular location: Cytoplasm; Secreted
Pathways (Reactome):
Immune System: Interleukin-36 pathway
Gene Ontology:
Molecular function: protein binding; interleukin-1 receptor antagonist activity; cytokine activity; interleukin-1 receptor binding
Biological process: antifungal humoral response; negative regulation of cytokine-mediated signaling pathway; negative regulation of interleukin-17 production; negative regulation of type II interferon production; cellular response to lipopolysaccharide; immune response; inflammatory response; signal transduction
Cellular component: cytoplasm; extracellular region
Genetic constraint (gnomAD): Loss-of-function variants: 11 observed, 13.88 expected, observed/expected ratio (o/e) 0.79, 90% interval 0.5 to 1.31. The upper end of that interval is the gene's LOEUF score, 1.31, which puts it in group 5 of 6, group 1 being the genes least tolerant of losing a copy. Missense variants: 195 observed, 204.86 expected, observed/expected ratio (o/e) 0.95, 90% interval 0.85 to 1.07. Synonymous variants: 94 observed, 89.21 expected, observed/expected ratio (o/e) 1.05, 90% interval 0.89 to 1.25.
Homologues: Orthologues: chimpanzee IL36RN (99% identical), macaque IL36RN (97% identical), dog IL36RN (91% identical), mouse Il36rn (91% identical), rat Il36rn (90% identical), guinea pig IL36RN (85% identical), zebrafish il1b (25% identical), zebrafish il1fma (22% identical). Paralogues in human: IL1RN (46% identical), IL1F10 (41% identical), IL37 (32% identical), IL36A (30% identical), IL36B (29% identical), IL36G (28% identical), IL1B (26% identical).
Diseases named in the same sentence as IL36RN in open-access papers:
IL36RN is named in the same sentence as 73 diseases in open-access papers, as found by Europe PMC text mining. Sharing a sentence is not in itself a finding about the gene and the disease. The quoted sentences say what the papers report.
psoriasis (45 papers, 2012 to 2025). An autoimmune condition characterized by red, well-delineated plaques with silvery scales that are usually on the extensor surfaces and scalp. "Several genes exemplified this scenario such as IL36G and IL36RN associated with psoriasis, and CSF3 associated with severe neutropenia." (PMID 40208878, 2025). "Most of the studies focused on treatment and pathogenesis of psoriasis revealed the presence of homozygous or heterozygous IL36RN variants in cases." (PMID 39992598, 2025). "Among the genes mapped to gene ontology biological processes and Reactome pathways, IL23R is linked to axial spondylarthritis, inflammatory bowel disease, and psoriasis, while IL36RN is associated with psoriasis." (PMID 39234544, 2024). "IL-36 receptor-deficient mice (Il36r–/–) were protected from IMQ-induced psoriasis-like dermatitis, whereas loss of IL-36Ra (Il36rn–/–) exacerbated disease severity." (PMID 38077370, 2023). "We identified a novel homozygous missense mutation in IL36RN in two siblings, and showed the molecular basis of the condition to be both distinct from psoriasis and distinct between the two families studied." (PMID 25688670, 2016). "Although EP is classified as a subtype of psoriasis, the pathogenic processes are distinct from those seen in plaque psoriasis, IL36RN mutations have been linked to pustular psoriasis, and the class I antigens HLA-Cw6, HLA-B57, HLA-B13, and HLA-B17 have been linked to psoriasis vulgaris." (PMID 39759759, 2024). "Furthermore, the C allele present in the rs7631529 SNP found in the IL36RN gene was correlated with an increased risk of psoriasis." (PMID 37569685, 2023). "IL36RN is mainly expressed in the esophagus and skin, and its encoded protein is a member of the IL-1 cytokine family, which plays an important role in the occurrence and development of asthma and psoriasis." (PMID 37723557, 2023). "Arguably, one of the most important discoveries leading to a better understanding of the pathogenesis of this exceptional type of psoriasis was the report of the association between IL36RN and GPP, which was shortly followed by other significant genetic findings." (PMID 34445754, 2021). "IL-36RN (receptor antagonist) gene mutation might play an important role in pustular forms of psoriasis like GPP (generalized pustular psoriasis) and acrodermatitis continua of Hallopeau." (PMID 33178709, 2020). "Loss-of-function mutations in the interleukin (IL)-36 gene IL36RN are associated with psoriasis." (PMID 33214582, 2020). "Furthermore, individuals with psoriasis showed a particularly severe, recalcitrant phenotype that carried both the IL36RN and AP1S3 mutations." (PMID 31736959, 2019). "Finally, from the genetics standpoint, only IL36RN gene (encodes an antagonist IL-36Ra for common IL-36 family receptor - IL-36R) polymorphisms have been analyzed to date, yealding associations with pustular form of psoriasis." (PMID 30634937, 2019). "Interestingly, IL36RN, the gene encoding the IL-36 receptor antagonist, is also highly up-regulated in all forms of psoriasis." (PMID 30054515, 2018). "While most research on IL36RN has focused on its role in autoimmune diseases, particularly psoriasis, the IL‐36 cytokine family has also been explored as a potential therapeutic target for various inflammatory conditions." (PMID 40347070, 2025). "The co-expression shifts of HKGs with psoriasis-associated genes (e.g., DEFB103A/B, S100A7A, IL36RN) further demonstrate their regulatory influence." (PMID 40959079, 2025). "While IL36RN has been extensively studied in autoimmune disorders such as psoriasis and inflammatory bowel disease, its role in cancer immunity remains poorly characterized." (PMID 40347070, 2025). "Next, we examined the effect of Cl-amidine, which is a pan-PAD inhibitor, in IMQ-induced psoriasis-like lesions of Il36rn−/− mice." (PMID 33214582, 2020).
psoriasis (continued). "Here, we aimed to clarify the role of NET signaling in DITRA and develop an effective therapy for IMQ-induced severe psoriasis in Il36rn−/− mice." (PMID 33214582, 2020). "As this information is merely comparison of the effect between Cl-amidine and DNase I, it strongly suggests that the inhibition of PAD4 by Cl-amidine suppressed NET formation and improved IMQ-induced psoriasis-like lesions in Il36rn−/− mice." (PMID 33214582, 2020). "Consistently, many psoriasis susceptibility genes encode the TRAF6 signaling players, such as ACT1 (TRAF3IP2), A20 (TNFAIP3), ABIN1 (TNIP1), IL-36Ra (IL36RN), IkappaBzeta (NFKBIZ), and CARD14." (PMID 31156649, 2019). "As compared to psoriasis, deficiency of IL-36R antagonist (DITRA) is a life-threatening monogenic type of disease caused by loss-of-function mutations in the IL36RN gene." (PMID 31736959, 2019). "The ILR-encoding genes associated with psoriasis are IL20RA, IL28RA, and IL36RN." (PMID 37569685, 2023). "IL36RN mutations are occasionally found in GPP patients with psoriasis, although GPP patients without psoriasis seem to have IL36RN mutations more frequently." (PMID 32153585, 2020). "In addition, TNF-α, CXCL1, IL-1β, IL-17A, and IL-36γ mRNA expression levels in IMQ-induced psoriasis-like lesions were significantly reduced by Cl-amidine administration compared to those in vehicle-treated Il36rn−/− mice." (PMID 33214582, 2020). "Furthermore, Cl-amidine-treated Il36rn−/− mice with psoriasis-like lesions showed decreased TNF-α, CXCL1, IL-1β, IL-36γ, and IL-17A expression compared to those in untreated, IMQ-induced Il36rn−/− mice." (PMID 33214582, 2020). "IMQ treatment for 3 consecutive days induced psoriasis-like lesions in Il36rn−/− mice." (PMID 33214582, 2020). "Recent identification of CARD14 as the psoriasis susceptible gene 2 and IL36RN mutations in generalized pustular psoriasis have defined new entities, CARD14-associated psoriasis (CAMPS) and deficiency of interleukin-36 receptor antagonist (DITRA), respectively." (PMID 32256502, 2020). "In addition, real-time RT-PCR analysis showed that IL-1β, IL-17A, IL-36γ, CXCL1, and CXCL2 expression was increased in IMQ-induced psoriasis-like lesions in Il36rn−/− mice." (PMID 33214582, 2020). "PLA2G4D, TGM1, and IL36RN are all described to be involved in the psoriasis." (PMID 27774448, 2016). "Given the various newly identified monogenic factors such as IL36RN and AP1S3 associated with significantly increased risk for psoriasis, perhaps the higher rate of consanguinity observed in the Middle East puts this population at greater risk for the development of psoriasis." (PMID 34977058, 2021). "Finally one of the most compelling evidence regarding a role of IL-36R signaling in psoriasis is the presence of a variety of IL36RN gene mutations leading to non-functional IL-36Ra in some patients with generalized pustular psoriasis." (PMID 25950182, 2015). "We revealed 479 differentially expressed genes between secukinumab and Dead Sea climatotherapy at the end of treatment, with a psoriasis panel identifying SERPINB4, SERPINB13, IL36G, IL36RN, and AKR1B10 as upregulated in Dead Sea climatotherapy compared with secukinumab." (PMID 38892277, 2024). "Furthermore, successful treatment of psoriasis with the anti-psoriatic standard treatment etanercept is accompanied by a decrease in IL36A, IL36G and IL36RN expression." (PMID 32484435, 2020). "In our study we only found IL36 cytokines (IL36G, IL36RN and IL36A) to be related to psoriasis." (PMID 25897967, 2015).
generalized pustular psoriasis (41 papers, 2013 to 2026). A rare and extreme form of psoriasis characterized by the appearance of sterile pustules which can take many patterns. "Mutations or deletions in IL36RN result in dysregulated IL‐36 activity, triggering excessive immune responses and contributing to severe manifestations of generalized pustular psoriasis." (PMID 40347070, 2025). "For example, favorable effects of treatment with IL-1 receptor antagonist anakinra were reported in a patient with generalized pustular psoriasis associated with IL36RN mutation." (PMID 38103162, 2023). "In fact, loss-of-function variants of the gene encoding IL-36Ra (IL36RN) are associated with generalized pustular psoriasis (GPP), a potentially life-threatening skin disorder presenting with recurrent pustular eruptions and systemic upset." (PMID 37414245, 2023). "In 2011, the role of IL36RN mutation resulting in IL-36Ra deficiency was first associated with a recessively inherited familial variant of generalized pustular psoriasis in 9 Tunisian families." (PMID 38103162, 2023). "Generalized pustular psoriasis is a potentially life-threatening skin disease, associated with IL36RN disease alleles." (PMID 37414245, 2023). "Genetic studies have reported pregnancy as predisposition to severe generalised pustular psoriasis for persons carrying the mutation of the interleukin 36 receptor antagonist gene (IL36RN genes)." (PMID 34441010, 2021). "Genome-wide association studies revealed that deficiency in interleukin-36 receptor antagonist due to IL36RN mutations was associated with generalized pustular psoriasis (GPP)." (PMID 32484435, 2020). "Loss-of-function mutations in IL36RN cause generalized pustular psoriasis (GPP), which is characterized by neutrophil-infiltrated lesions." (PMID 31959814, 2020). "Mutation of the IL36RN gene, encoding interleukin-36 receptor antagonist (IL-36Ra), is associated with generalized pustular psoriasis, but IL36RN mutations in Chinese palmoplantar pustulosis patients have not previously been investigated." (PMID 31789248, 2019). "Recessive mutations in IL36RN, coding for the IL-36 receptor antagonist, have been associated with generalized pustular psoriasis (GPP)." (PMID 30909615, 2019). "Patients with a functional deficiency in the IL-36Rn gene encoding for the antagonist IL-36Ra suffer from severe generalized pustular psoriasis." (PMID 28611508, 2017). "Other phenotypes of the IL36RN mutation include related pustular disorders, palmoplantar pustulosis, acrodermatitis continua of Hallopeau (ACH), and acute generalized exanthematous pustulosis." (PMID 28421071, 2017). "Of pivotal importance is the observation that mutations of IL36-RN (gene encoding IL-36Ra) have also been shown to cause generalised pustular psoriasis (GPP), the most severe and potentially life threatening form of psoriatic inflammation." (PMID 27101808, 2016). "Several reports identified a homozygous missense mutation in IL36RN that encodes IL36Ra in patients with familial generalized pustular psoriasis and found that the mutations in IL36RN cause poor affinity or labile binding of IL-36Ra to IL-36R." (PMID 26549942, 2015). "In patients with generalized pustular psoriasis (GPP), Li Ming found that there was a statistically significant difference in the mutation frequency of the IL36RN gene carried by pediatric generalized pustular psoriasis (PGPP) and adult generalized pustular psoriasis (AGPP) (P = 0.008)." (PMID 40176872, 2025). "Homozygous or compound heterozygous mutations in the IL36RN gene have been implicated in psoriasis-related pustular eruptions, such as generalized pustular psoriasis, acrodermatitis continua of Hallopeau, acute generalized exanthematous pustular eruptions, and palmoplantar pustular psoriasis." (PMID 35927298, 2022). "Consequently, a few Japanese individuals carry IL36RN mutations, which may have etiological roles in several diseases, including generalized pustular psoriasis." (PMID 35927298, 2022).
generalized pustular psoriasis (continued). "Moreover, previous researches mentioned that IL36RN mutation may promote general pustular psoriasis (GPP), a rare type of life‐threatening disease." (PMID 34272761, 2021). "Thus, many Japanese have IL36RN mutations that could be the pathogenic factor for many diseases, including generalised pustular psoriasis." (PMID 31959814, 2020). "Homozygous or compound heterozygous IL36RN gene mutations underlie the pathogenesis of psoriasis-related pustular eruptions, including generalised pustular psoriasis, palmoplantar pustular psoriasis, acrodermatitis continua of Hallopeau, and acute generalised exanthematous pustular eruptions." (PMID 31959814, 2020). "Interleukin-36-receptor antagonist deficiency is a hereditary auto-inflammatory disease characterized by repeated flares of generalized pustular psoriasis (GPP)." (PMID 24131530, 2013). "Heterozygous and homozygous MPO variants were reported in several cases of generalized pustular psoriasis (GPP) and some of the cases had also one or two IL36RN gene variants and the other had only one or two MPO variants." (PMID 39992598, 2025). "This was followed by the MVK, NLRP12, and IL36RN genes causing hyper IgD syndrome, (HIDS) and generalized pustular psoriasis (GPP) with 2 unique variants each, in 8 and 4 individuals, respectively." (PMID 34905135, 2021). "Taking generalized pustular psoriasis (GPP) as an example, IL36RN mutations were common in GPP patients, especially in patients without associated plaque psoriasis." (PMID 34675805, 2021). "A similar disorder results from a rare inactivating mutation in the gene encoding IL-36Ra, IL36RN, and is manifested as a severe inflammation of the skin referred to as generalized pustular psoriasis (GPP)." (PMID 31231388, 2019). "Recent studies have revealed associations of generalized pustular psoriasis with mutations in the genes of CARD14 and IL36RN and, as a consequence, several studies to block either IL-36 or the IL-36 receptor (IL-36R) are underway." (PMID 29963046, 2018). "Defects in IL-36R signaling have been described in generalized pustular psoriasis (GPP), where heterozygous, compound heterozygous and homozygous mutations in the gene encoding IL-36RA (IL36RN) lead to the rare deficiency of interleukin thirty-six–receptor antagonist (DITRA) syndrome." (PMID 40447918, 2025). "Notably, elevated IL-36 cytokine pathway activity is implicated in the pathogenesis of generalized pustular psoriasis (GPP), as up to 1/3 of GPP patients have missense mutations in IL-36RN, which inhibits IL-36 receptor activation." (PMID 38067173, 2023). "Mutations in IL36RN may have a definite effect on pathological similarities between AGEP and generalized pustular psoriasis." (PMID 29226159, 2017). "However, many patients with generalized pustular psoriasis and the vast majority of localized pustular psoriasis do not share mutations in the IL-36RN gene." (PMID 29963046, 2018).